ENSG00000280904
Gene: Small nucleolar RNA gene on chromosome 3 (52,688,882 to 52,688,961, forward strand). Ensembl gene ENSG00000280904.
Homologues: Orthologues: mouse Gm23852 (48% identical). Paralogues in human: SNORD19B (65% identical).